P4HA1 (prolyl 4-hydroxylase subunit alpha 1)
Diseases named in the same sentence as P4HA1 in open-access papers (continued):
Sharing a sentence is not in itself a finding about the gene and the disease.
colorectal cancer (11 papers, 2019 to 2025). A primary or metastatic malignant neoplasm that affects the colon or rectum. "Among these genes, P4HA1 exhibited a positive regression coefficient, suggesting its potential role as a risk factor, with higher expression levels correlating with worse clinical outcomes in colorectal cancer." (PMID 40959429, 2025). "P4HA1 facilitates the advancement of colorectal cancer, while its suppression diminishes the in vitro proliferation and migration of colorectal cancer cells." (PMID 40959429, 2025). "To elucidate the functional significance of P4HA1, a core gene identified in our prognostic signature, we further examined its involvement in colorectal cancer (CRC) progression." (PMID 40959429, 2025). "Previous studies have reported similar observations about the role of P4HA1 in promoting invasion in different cancer types, including glioblastoma and colorectal cancer." (PMID 40332386, 2025). "Silencing P4HA1 markedly reduces the proliferative and migratory abilities of colorectal cancer cells in vitro." (PMID 40959429, 2025). "A recent study identified CA-074Me as a specific cell-permeable CTSB inhibitor and small-molecule inhibitor diethyl-pythiDC that targets P4HA1 has been used for treating colorectal cancer." (PMID 34771678, 2021). "To evaluate the prognostic potential of P4HA1 for early stage colorectal cancer, we examined the relationship between patient survival time and P4HA1 expression using Kaplan-Meier analysis." (PMID 32166002, 2020). "Another study revealed that P4HA1 hypoxia-induced P4HA1 overexpression could promote colorectal cancer progression." (PMID 34966739, 2021). "Since KRAS mutations occur frequently in colorectal cancer, we asked whether KRAS mutation enrichment in the P4HA1-high group may contribute to poor prognosis in early stage CRC." (PMID 32166002, 2020). "Our study provides strong support for P4HA1 as a predictive protein marker for precision diagnostics, therapeutic decision-making, and drug development for early stage colorectal cancer and demonstrates the utility of proteomic profiling to identify novel protein biomarkers." (PMID 32166002, 2020).
head and neck squamous cell carcinoma (10 papers, 2019 to 2022). A squamous cell carcinoma that arises from any of the following anatomic sites: lip and oral cavity, nasal cavity, paranasal sinuses, pharynx, larynx, and salivary glands. "Upregulation of P4HA1 promotes cell migration and invasion in glioblastoma and head/neck squamous cell carcinoma and, in this way, provides a biomarker for poor prognosis in patients with high expressions of P4HA1." (PMID 34217310, 2021). "In addition, P4HA1 and P4HA2 are confirmed hypoxia-associated genes and associated with poor prognosis in head and neck squamous cell carcinoma." (PMID 31467922, 2019). "For example, a 7-mRNA signature (AATF, APP, GNPDA1, HPRT1, LASP1, P4HA1 and ILF3) of head and neck squamous cell carcinoma (HNSCC) shows a moderate predictive ability for 5-year OS (AUC for training set, 0.75; testing set, 0.66)." (PMID 31396442, 2019). "However, the association between P4HA1 and head and neck squamous cell carcinomas (HNSCC) has not been thoroughly elucidated to date." (PMID 31782831, 2020).
hepatocellular carcinoma (9 papers, 2017 to 2024). A malignant tumor that arises from hepatocytes. "P4HA1 encodes a component of proline 4-hydroxylase, a key enzyme in collagen synthesis, which is associated with liver fibrosis and hepatocellular carcinoma." (PMID 38601640, 2024). "miR-30e inhibits the proliferation of hepatoma cells through directly targeting the 3′-UTR of P4HA1 mRNA." (PMID 29052520, 2017). "Consistently, it has been found that hypoxia-related genes CA9, NDRG1, SLC2A1, P4HA1 and ENO1 induced EMT in hepatocellular carcinoma, bladder cancer, laryngeal cancer and gastric cancer, respectively." (PMID 34136390, 2021).
oral squamous cell carcinoma (8 papers, 2020 to 2025). "High P4HA1 mRNA level was reported to be significantly associated with unfavorable OS and locoregional recurrence of oral squamous cell carcinoma, indicating that P4HA1 might act as a potent tumor promoter." (PMID 32933024, 2020). "We also found that the expression of P4HA1–2 proteins was higher in oral squamous cell carcinoma tissues than in normal oral mucosal tissues." (PMID 38806556, 2024). "In oral squamous cell carcinoma, a high P4HA1 mRNA level was reported to be a single-gene surrogate of hypoxia and an independent prognostic marker for locoregional recurrence and OS." (PMID 32166002, 2020). "As P4HA2 regulates the PI3K/AKT signaling pathway in oral squamous cell carcinoma, we detect whether P4HA1 can regulate the PI3K/AKT signaling pathway via P4HA2 in CRC." (PMID 41469036, 2025). "Interestingly, one research suggested that those three hypoxia signatures might be replaced by P4HA1 and another study also confirmed that P4HA1 was a significantly prognostic factor for oral squamous cell carcinoma patients." (PMID 33061850, 2020).
ovarian carcinoma (8 papers, 2018 to 2025). A malignant neoplasm originating from the surface ovarian epithelium. "Previous studies have demonstrated that the propyl-4-hydoxylases P4HA1 and 2 are upregulated by hypoxia in epithelial ovarian cancer cells exposed to hypoxia, and high expression is associated with decreased survival in patients with ovarian cancer." (PMID 40867253, 2025). "MiR-122 and P4HA1 may be potential diagnostic markers and therapeutic targets in ovarian cancer." (PMID 39568592, 2024). "Previous studies have demonstrated that miR-122-5p inhibits the migration, invasion, and metastasis of ovarian cancer cells by targeting the P4HA1 gene." (PMID 38793064, 2024).
lung adenocarcinoma (7 papers, 2020 to 2024). A carcinoma that arises from the lung and is characterized by the presence of malignant glandular epithelial cells. "To investigate the role of P4HA1 expression in lung adenocarcinoma progression, we assessed the association of clinicopathological features with P4HA1 mRNA and protein expression." (PMID 34659558, 2021). "To get insight into the biological functions and potential molecular pathways of P4HA1 implicated in the tumorigenesis of lung adenocarcinoma, we carried on the Gene enrichment analysis with TCGA LUAD Cohort." (PMID 34659558, 2021). "We found that P4HA1 was significantly overexpressed in lung adenocarcinoma compared with adjacent normal tissues and was associated with clinicopathological stages, poor OS, and DSS." (PMID 34966739, 2021). "Additionally, we discovered that high CNA was associated with high expression of P4HA1 in lung adenocarcinoma." (PMID 34966739, 2021). "We detected P4HA1 expression in cisplatin-resistant cell lines to demonstrate whether P4HA1 is associated with chemoresistance in lung adenocarcinoma." (PMID 34659558, 2021). "P4HA1 has recently been found to be a prognostic biomarker in pan-cancer, especially in lung adenocarcinoma." (PMID 39021802, 2024). "The expression of P4HA1 in cisplatin-resistant lung adenocarcinoma remarkably increased compared with control groups." (PMID 34659558, 2021). "To detect the function of P4HA1 in the stemness of lung adenocarcinoma, we applied cancer cell sphere formation analysis." (PMID 34659558, 2021). "We also analyzed with TCGA lung samples with follow-up data that the prognostic value of increased expression of P4HA1 in lung adenocarcinoma and lung squamous cancer, separately." (PMID 34659558, 2021). "In our study, we identified that P4HA1 increased in both lung adenocarcinoma and lung squamous cell carcinoma." (PMID 34659558, 2021). "In the cohort, P4HA1 showed distinct differential expression in both lung adenocarcinoma and lung squamous cell carcinoma compared with normal lung tissue." (PMID 34659558, 2021). "Our in vitro study validated that decreased P4HA1 expression inhibited the proliferation, migration and invasion of lung adenocarcinoma cells." (PMID 34659558, 2021). "In this study, our cancer cell sphere formation analyses firstly demonstrated that knockdown P4HA1 increased the numbers and diameter of lung adenocarcinoma cell spheres." (PMID 34659558, 2021). "Since P4HA1 displayed greater prognostic value in lung adenocarcinoma, we will focus on lung adenocarcinoma in our further study." (PMID 34659558, 2021). "A study has reported that prolyl 4-hydroxylase subunit alpha 1, which regulates cyclin-dependent kinases (CDKs), cyclins, and CDK inhibitors, was associated with EMT, tumor cell invasion and metastasis of lung adenocarcinoma." (PMID 34830941, 2021). "Transwell migration assays demonstrated that knockdown P4HA1 inhibited the ability of tumor cell migration in lung adenocarcinoma." (PMID 34659558, 2021). "In this study, we use bioinformatic analysis to explore the prognostic value of P4HA1 in lung adenocarcinoma (LUAD) and the relationship with prognosis and tumor-infiltrating immune cells (TIICs)." (PMID 33299876, 2020). "Research has shown that P4HA1 is essential for the growth and invasion of lung cancer cells, indicating that P4HA1 may be an effective therapeutic target for lung adenocarcinoma." (PMID 39568592, 2024). "Besides, lung adenocarcinoma cells with P4HA1 knockdown showed decreasing OCT4, SOX2, NANOG protein levels." (PMID 34659558, 2021). "After analyzing the relationship between P4HA1 and clinical pathological parameters of lung adenocarcinoma patients, we found P4HA1 mRNA expression relating to tumor diameters and distant metastasis, while not relating to age, gender, smoking history and clinical stage." (PMID 34659558, 2021).
lung adenocarcinoma (continued). "In addition, we analyzed the connection between P4HA1 expression and immune cells in lung adenocarcinoma using three distinct immune cell infiltration datasets and three distinct analysis methods." (PMID 34966739, 2021). "In summary, all of the analysis above suggests that P4HA1 may be a valuable modulator in lung adenocarcinoma." (PMID 34659558, 2021). "According to the gene enrichment analysis, P4HA1 may regulate the proliferation of lung adenocarcinoma by regulating cell cycle." (PMID 34659558, 2021). "Moreover, Matrigel invasion assay indicated that knockdown of P4HA1 significantly inhibited tumor cell invasion of lung adenocarcinoma." (PMID 34659558, 2021). "We used flow cytometry cell cycle to identify whether knockdown P4HA1 could inhibit proliferation of lung adenocarcinoma cells via affecting cell cycle." (PMID 34659558, 2021). "Taken together, these results indicated that P4HA1 might serve as an independent prognostic biomarker for lung adenocarcinoma patients." (PMID 34659558, 2021). "Hence, we hypothesized that P4HA1 may promote proliferation and distant metastasis of lung adenocarcinoma." (PMID 34659558, 2021). "Besides, dysregulation of P4HA1 inhibited the stemness and chemoresistance of lung adenocarcinoma." (PMID 34659558, 2021). "Therefore, our hypothesis was that P4HA1 may involve in the proliferation and metastasis of lung adenocarcinoma." (PMID 34659558, 2021). "Moreover, via inhibiting epithelial-mesenchymal transition (EMT) and matrix metalloprotease (MMPs), dysregulation of P4HA1 could restrain the tumor cell invasion and metastasis of lung adenocarcinoma." (PMID 34659558, 2021). "In addition, we found that P4HA1 could enhance cell stemness and cisplatin-resistance in lung adenocarcinoma." (PMID 34659558, 2021). "Additionally, our study focused on P4HA1 impact on lung adenocarcinoma." (PMID 34966739, 2021). "Moreover, we investigated with the Cox regression, both univariate and multivariate process to validate whether P4HA1 could serve as an independent prognostic biomarker in lung adenocarcinoma." (PMID 34659558, 2021). "Hence, we assumed that P4HA1 might involve in stem cell function of lung adenocarcinoma." (PMID 34659558, 2021). "Consequently, P4HA1 may be a promising therapeutic target for lung adenocarcinoma." (PMID 34659558, 2021). "And we demonstrated that P4HA1 protein expression was correlated with poor overall survival in lung adenocarcinoma, and was not correlated in lung squamous cell carcinoma." (PMID 34659558, 2021). "We found that P4HA1 protein increased in lung cancer tissues compared to non-cancerous lung tissues in both lung adenocarcinoma and lung squamous cell carcinoma." (PMID 34659558, 2021). "Besides, overexpressed P4HA1 is correlated with poor clinical outcomes and serve as an independent prognosis biomarker in lung adenocarcinoma (LUAD), but not lung squamous cell carcinoma (LUSC)." (PMID 34659558, 2021). "Furthermore, P4HA1 was correlated with poor prognosis and served as an independent prognosis biomarker for lung adenocarcinoma, but not lung squamous cell carcinoma." (PMID 34659558, 2021). "Kaplan-Meier analysis revealed that P4HA1 was negatively correlated to overall survival (OS), disease-specific survival (DSS), and progression free interval (PFI), but not with disease-free interval (DFI) in lung adenocarcinoma." (PMID 34659558, 2021).
lung carcinoma (7 papers, 2021 to 2025). "In line with this, recent studies have associated P4HA1 with clinically important cancer phenotypes, with correlation of P4HA1 expression with cancer stage and poor prognosis in breast and lung cancers, among others." (PMID 40332386, 2025). "The experiments on silencing P4HA1 also confirm its crucial role in lung cancer growth, migration, and invasion." (PMID 39329988, 2024). "This explains why P4HA1 is better characterized for its role in lung cancer, whereas P4HA2 is well known for its role in glioma and cervical cancer." (PMID 39329988, 2024). "We investigated P4HA1 expression in six different lung cancer cells and human bronchial epithelial cell line with real-time PCR and Western blotting." (PMID 34659558, 2021). "GTEx-TCGA lung cancer cohort having the largest samples were first selected to assessed the mRNA expression of P4HA1 in our study." (PMID 34659558, 2021). "The results indicated P4HA1 was highly expressed in six lung cancer lines in both mRNA and protein level, in which A549 and SPC-A1 were the two most high expressed adenocarcinoma cell lines." (PMID 34659558, 2021). "In lung cancer, P4HA1 is essential for migration, growth, and invasion." (PMID 40332386, 2025). "Furthermore, P4HA1 inhibitors have the potential to become a treatment for lung cancer." (PMID 39568592, 2024). "Consequently, the development of highly specific and potent P4HA1 inhibitors may be the key to overcome chemotherapy resistance and improve lung cancer treatment." (PMID 34659558, 2021). "In summary, P4HA1 plays a crucial role in the development of NSCLC and may provide a brand-new target for lung cancer treatment." (PMID 34659558, 2021). "However, there has been no detailed investigation of the role of P4HA1 in lung cancer." (PMID 34659558, 2021).
glioblastoma (6 papers, 2021 to 2025). The most malignant astrocytic tumor (WHO grade IV). "P4HA1 was also shown to promote glioblastoma cell migration and invasion by facilitating the EMT process in hypoxic microenvironments and to be an enzyme essential for vasifaction and maintenance of vascular wall integrity in malignancies." (PMID 35494018, 2022). "P4HA1, an enzyme involved in collagen hydroxylation and hypoxia response, has been recently shown to regulate succinylation in glioblastoma by increasing intracellular succinate and enhancing PGK1 K191/K192 succinylation, which stabilizes PGK1 and promotes aerobic glycolysis via the HIF1α/ATF3 axis." (PMID 40463370, 2025). "While P4HA1 is widely expressed and highly conserved in various cell types, playing a role in glioblastoma stem-like cell transition and inducing epithelial–mesenchymal transition in glioblastoma, our study is the first to link P4HA1 to ischemia-induced angiogenesis." (PMID 38238754, 2024). "Furthermore, hypoxia can promote the metastasis of glioblastoma multiforme (GBM) via the L-Arg/P4HA1 axis, and an increased P4HA1 is associated with poor prognosis and advanced histological grade." (PMID 35812752, 2022).
liver fibrosis (6 papers, 2015 to 2025). "CDCA also reduced hypoxic induction of other HIF-1α target genes such as lysyl oxidase (LOX) and collagen prolyl-4 hydroxylase A1 (P4HA1) which are involved in hepatic fibrosis." (PMID 26098428, 2015). "Further, the inhibition of P4ha1 might decrease collagen production and work as a therapeutic for treating liver fibrosis." (PMID 39218217, 2024). "As liver fibrosis is characterized by excess deposition of collagen, the upregulation of p4ha1 suggests that liver fibrosis may be induced in zebrafish under HCD." (PMID 39218217, 2024).
colon adenocarcinoma (5 papers, 2020 to 2025). "This process yielded a four-gene signature—PDSS2, GRSF1, SLC39A8, and P4HA1—with significant prognostic value in colon adenocarcinoma." (PMID 40959429, 2025). "P4HA1 is also a novel glycolysis-related gene in predicting the survival patients with colon adenocarcinoma." (PMID 39021802, 2024).
colon cancer (5 papers, 2021 to 2026). "qRT-PCR was performed from RNA extracted from 43 pairs of colon cancer and adjacent normal tissues to observe the relative expression levels of eight GRGs (P4HA1, STC2, CHPF2, PMM2, PGM2, ENO3, PPARGC1A, and PPP2CB)." (PMID 34422808, 2021). "Therefore, CDC25C and P4HA1 have the potential to serve as biomarkers for COAD patients and contribute to the decision-making process regarding colon cancer treatment." (PMID 36273131, 2022).
gastric cancer (5 papers, 2021 to 2022). A primary or metastatic malignant neoplasm involving the stomach. "Low expression of P4HA1 was related to poor OS, first progression, and post-progression survival in gastric cancer and poor PFS in liver cancer." (PMID 35812752, 2022).
head and neck cancer (5 papers, 2021 to 2023). A primary or metastatic malignant neoplasm affecting the head and neck. "Findings from recent studies have shown that P4HA1 is up-regulated in lung, breast and head/neck cancer tissues, and high expression levels of P4HA1 are significantly correlated with the clinical characteristics of these cancers." (PMID 34217310, 2021).
liver cancer (5 papers, 2017 to 2024). An epithelial or non-epithelial malignant neoplasm that arises from the liver. "We conducted a meta-analysis to further verify the correlation between P4HA1 expression and prognosis in breast, ovarian, lung, gastric, and liver cancers." (PMID 35812752, 2022). "Further studies demonstrated that the effect of miR-30e in liver cancer may be through targeting MTA1 for epithelial to mesenchymal transition and P4HA1 for proliferation suppression." (PMID 28969071, 2017).